5_8S_rRNA (5.8S ribosomal RNA )
Synonyms: RNA5-8SP10
Gene: Ribosomal RNA gene on chromosome 21 (8,256,781 to 8,256,933, forward strand). Ensembl gene ENSG00000277739.
Gene Ontology:
Molecular function: structural constituent of ribosome
Cellular component: ribosome
Homologues: Orthologues: chimpanzee 5_8S_rRNA (100% identical), macaque 5_8S_rRNA (100% identical), rabbit 5_8S_rRNA (100% identical), rat 5_8S_rRNA (100% identical). Paralogues in human: 5_8S_rRNA (100% identical), RNA5-8SN1 (100% identical), RNA5-8SN2 (100% identical), RNA5-8SN3 (100% identical), RNA5-8SN4 (100% identical), RNA5-8SN5 (100% identical), 5_8S_rRNA (90% identical), 5_8S_rRNA (87% identical), 5_8S_rRNA (86% identical).